ATG3 (autophagy related 3)
Diseases named in the same sentence as ATG3 in open-access papers (continued):
Sharing a sentence is not in itself a finding about the gene and the disease.
leukemia (4 papers, 2016 to 2023). A malignant (clonal) hematologic disorder, involving hematopoietic stem cells and characterized by the presence of primitive or atypical myeloid or lymphoid cells in the bone marrow and the blood. "Here, we present data on the mechanisms by which leukemia cells maintain their cell survival after inhibition of autophagy by the loss of ATG3." (PMID 34885250, 2021). "In order to understand the mechanism contributing to cell survival in ATG3 deficiency we examined the dependency of leukemia cells on glycolysis or OXPHOS." (PMID 34885250, 2021). "After the loss of ATG3, leukemia cells upregulated their energy metabolism by increasing glycolysis and mitochondrial metabolism, in particular oxidative phosphorylation, which resulted in higher ATP levels." (PMID 34885250, 2021). "By genetically depleting ATG3 in human leukemia cell lines, we demonstrate that AML cells rewire their energy metabolism to sustain cell survival when autophagy is impaired." (PMID 34885250, 2021). "As our data demonstrated that leukemia cells can survive the inhibition of ATG3-dependent autophagy, we wanted to elucidate the mechanism contributing to maintaining cellular homeostasis and survival." (PMID 34885250, 2021). "In this study, we identified ATG3 as a key player for survival of leukemia cells and present conclusive evidence supporting that upon loss of ATG3 AML cells rewire their central carbon metabolism to evade survival disruption upon autophagy inhibition." (PMID 34885250, 2021). "A gene expression microarray study revealed that ATG3 was downregulated in myelodysplastic syndrome patients and patients progressing to leukemia." (PMID 34235149, 2021). "Downregulation of Atg3 expression was detected in four leukemia cell lines compared with healthy bone marrow cells." (PMID 27391105, 2016). "Both the Atg3 mRNA and protein expression were decreased in all four leukemia cell lines compared to healthy bone marrow cells." (PMID 27391105, 2016). "The current study showed that Atg3 was downregulated in leukemia cell lines compared to healthy bone marrow cells." (PMID 27391105, 2016). "According to a gene expression microarray, atg3 is downregulated in MDS patients progressing to leukemia, but less is known about the function of Atg3 in the survival and death of MSD/AML cells." (PMID 27391105, 2016). "To investigate the potential role of Atg3 in leukemia cells, we first analyzed the expression of Atg3 by real-time PCR and Western blotting in bone marrow cells of healthy people and human leukemia cell lines (SKM-1, THP-1, NB4, and K562)." (PMID 27391105, 2016). "Hence, ATG3 could be a potential target for treating leukemia by increasing its expression or specifically inhibiting its degradation if specific mutations can be excluded." (PMID 34235149, 2021). "Four leukemia cell lines (SKM-1, THP-1, NB4 and K562) and two healthy patients’ bone marrow cells were analyzed for Atg3 expression via qRT-PCR and Western blotting analysis." (PMID 27391105, 2016). "However, hematopoietic cells expressing BCR-AbI (a constitutively active oncogenic kinase) are highly sensitive to autophagy and fail to generate leukemia cells without ATG3." (PMID 34235149, 2021).
bladder cancer (3 papers, 2019 to 2021). "In our study, the autophagy process induced by C-2 is associated with autophagy factors such as ATG7, ATG5, ATG3, p62, LC3 and Beclin-1, therefore, the ability of C-2 to induce autophagy in bladder cancer cell lines was confirmed." (PMID 31685029, 2019).
cervical cancer (3 papers, 2020 to 2024). A primary or metastatic malignant neoplasm involving the cervix. "Following prediction, ATG3 was an underlying downstream target of cervical cancer." (PMID 34567283, 2021). "Western blot data confirmed the upregulation of ATG3 proteins in cervical cancer than normal samples (p < 0.0001)." (PMID 34567283, 2021). "From TCGA database, we firstly assessed ATG3 expression in cervical cancer tissue specimens." (PMID 34567283, 2021). "Collectively, this study showed that cancer-derived exosomal miR-651 may restrain cisplatin resistance and progression and directly targeted ATG3 in cervical cancer." (PMID 34567283, 2021). "Putting together, ATG3 was a target of miR-651 and forced miR-651 may lessen ATG3 expression in cervical cancer." (PMID 34567283, 2021). "In the present study, we identified ATG3 as a favorable prognostic factor in cervical cancer." (PMID 33160404, 2020). "Thus, cancer-derived exosomal miR-651 could restrain malignant behaviors of cervical cancer cells through ATG3." (PMID 34567283, 2021). "Also, we detected ATG3 expression in plasma samples from cervical cancer and normal individuals." (PMID 34567283, 2021). "This study then evaluated whether miR-651 impacted ATG3 expression in cervical cancer cells." (PMID 34567283, 2021). "Moreover, forced exosomal miR-651 could restrain cisplatin resistance and directly target ATG3 for cervical cancer cells, suggesting the action of miR-651 on cervical cancer progress." (PMID 34567283, 2021). "Thus, ATG3 may be a direct target of miR-651 in cervical cancer." (PMID 34567283, 2021).
colorectal cancer (3 papers, 2022 to 2023). A primary or metastatic malignant neoplasm that affects the colon or rectum. "This stabilization of the ATG3 protein level attenuates the radiosensitivity of colorectal cancer." (PMID 38137461, 2023). "Further studies have revealed that in colorectal cancer, the long non-coding RNA (lncRNA) SP100-AS1 regulates cellular autophagy by modulating the level of ATG3 ubiquitylation." (PMID 38137461, 2023). "Consistently, NEAT1 also induces autophagy by targeting miR-34a and miR-204 as a competing endogenous RNA (ceRNA) in colorectal cancer and HCC, respectively, resulting in the upregulation of autophagy-related proteins ATG9A, ATG4A, and ATG3." (PMID 36430876, 2022).
glioma (3 papers, 2019 to 2022). A benign or malignant brain and spinal cord tumor that arises from glial cells (astrocytes, oligodendrocytes, ependymal cells). "To ascertain whether induction of CD8 T cell infiltration was connected to increased levels of autophagic flux upon IM + anti-VEGF treatment, we silenced the expression of ATG3, a key regulator of autophagy, in glioma-derived cells, which were implanted into the brains of immunocompetent animals." (PMID 36113478, 2022). "The results showed that mRNA expression of ATG3 (HR = 0.63, 95% CI: 0.40–0.99, p = 0.05), ATG4C (HR = 1.54, 95% CI: 1.16–2.01, p = 3 × 10− 3) and ATG5 (HR = 0.61, 95% CI: 0.43–0.86, p = 5 × 10− 3) were independent OS prognostic factors in gliomas patients." (PMID 31291988, 2019).
Insulin resistance (3 papers, 2023 to 2024). Increased resistance towards insulin, that is, diminished effectiveness of insulin in reducing blood glucose levels. "The results of a study on the rat model of NAFLD treated with an inhibitor of JNK showed that the expression levels of ATG3 and ATG5 were decreased, insulin resistance was reduced, and NAFLD was improved." (PMID 37876013, 2023). "Besides, Lingguizhugan Decoction improved insulin resistance in overweight/obese patients with MASLD by increasing the levels of DNA N6-methyladenine modification of protein phosphatase 1 regulatory subunit 3A (PPP1R3A) and autophagy related 3 (ATG3)." (PMID 39440040, 2024).
tuberculosis (3 papers, 2018 to 2022). A chronic, recurrent infection caused by the bacterium Mycobacterium tuberculosis. "Hence, developing novel drugs that would boost autophagy is a new therapeutic strategy against tuberculosis, or drugs targeting miR/lncR to promote ATG3 expression might be an underlying tool to clear pathogens." (PMID 34235149, 2021). "Taken together, our findings suggest how Mtb can manipulate cellular miRNA expression to regulate Atg3 for its own survival, and highlight the importance to develop novel therapeutic strategies against tuberculosis that would boost autophagy." (PMID 29300789, 2018).
acute myeloid leukemia (2 papers, 2021 to 2023). Acute myeloid leukemia (AML) is a group of neoplasms arising from precursor cells committed to the myeloid cell-line differentiation. "PU.1 is a positive transcriptional regulator of ATG3, and low expression of PU.1 may account for the low expression of ATG3 in acute myeloid leukemia." (PMID 34235149, 2021). "Autophagy-related proteins such as ULK1, ATG3, ATG5, ATG13, and ATG14 were markedly expressed in various acute myeloid leukemias when comparing the microarray-based expression profiling of distinct ATG proteins from human AML samples with the human normal hematopoiesis." (PMID 37180758, 2023).
asthma (2 papers, 2021 to 2022). "Although ATG3 is a key central regulator in autophagy induction during aging, and NUF2 is closely associated with lung cell senescence, their specific role in asthma has rarely been studied." (PMID 34136532, 2021). "Moreover, except for ATG3, HDAC1, and TGFB1, correlation analysis showed that the expression of the aging-related genes in peripheral blood of asthma patients was associated with pulmonary function parameters (FEV1%, FEV1, FVC, PEF, FEF75, FEF50, and FEF25)." (PMID 34136532, 2021). "ATG3 expression gradually increased in patients with CRS without nasal polyps, patients with CRSwNP, and mice with CRSwNP/asthma, suggesting a strong link between autophagy and the development of CRS." (PMID 35747690, 2022).
Cerebral ischemia (2 papers, 2022 to 2025). Restriction of arterial blood supply to the brain associated with insufficient oxygenation to support the metabolic requirements of the tissue. "The levels of autophagy-related proteins, including Beclin-1, Atg3, Atg5, and LC3 in the hippocampus were effectively maintained and elevated at 28 days after cerebral ischemia/reperfusion in the young gerbils compared with those in the old gerbils." (PMID 35220404, 2022).
cervical squamous cell carcinoma (2 papers, 2020 to 2021). A squamous cell carcinoma arising from the cervical epithelium. "We carried out a multivariate Cox regression analysis and developed six ARG-related prognostic signature for the survival prediction of patients with squamous cell cervical cancer (Risk score = − 0.63*ATG3–0.42*BCL2 + 0.85*CD46–0.38*IFNG+ 0.23*NAMPT+ 0.82*TM9SF1)." (PMID 33160404, 2020). "Next, we carried out multivariate Cox regression analysis and identified 6 genes (ATG3, BCL2, CD46, IFNG, NAMPT, TM9SF1) that were independently associated with OS in squamous cell cervical cancer patients." (PMID 33160404, 2020). "After univariate and multivariate Cox regression assay of differentially expressed ARGs, 6 ARG (ATG3, BCL2, CD46, IFNG, NAMPT, TM9SF1) related prognostic signatures for squamous cell cervical cancer were constructed." (PMID 33160404, 2020).
emphysema (2 papers, 2023 to 2025). "Proteomics analysis indicated that autophagy could be involved in antibiotic-associated emphysema aggravation, and increased protein levels of LC3B, atg3, and atg7 were identified by Western blotting." (PMID 37779147, 2023). "SCFA administration restored emphysema development with reduced inflammatory cells, IL-6, and IFNγ and decreased LC3B, atg3, and atg7 levels." (PMID 37779147, 2023).
fatty liver (2 papers, 2016 to 2022). "Knockdown of ATG3 in human hepatocyte ameliorated hepatic steatosis condition while overexpression of ATG3 increased lipid load in hepatocytes." (PMID 35909524, 2022).
malaria (2 papers, 2015 to 2023). Malaria is a serious and sometimes fatal disease caused by a parasite that commonly infects a certain type of mosquito which feeds on humans. "Consistent with the AF2 predictions, ATG3 from the malaria parasite (Plasmodium falciparum) was found to have a noncanonical AIM in this region with the WLLP sequence." (PMID 36753519, 2023).
melanoma (2 papers, 2017 to 2020). A malignant, usually aggressive tumor composed of atypical, neoplastic melanocytes. "We performed western blot analysis to examine the expressions of autophagy-related proteins and the results showed that (+)-bornyl p-coumarate induced autophagy in melanoma cells, upregulating the protein levels of Beclin-1, LC3-I, LC3-II, Atg5, Atg3 and p62." (PMID 32466337, 2020). "SIRT6 knockdown was found to cause a marked decrease in the protein levels of LC3 II (autophagy related form of LC3), ATG3, ATG7, SQSTM1 and BECN in melanoma cells." (PMID 29234488, 2017). "Moreover, increased expressions of beclin-1, Atg3, Atg5, p62, LC3-I and LC3-II proteins and suppression by autophagic inhibitor 3-methyladenine (3-MA), indicated that (+)-bornyl p-coumarate triggered autophagy in the melanoma cells." (PMID 32466337, 2020).
Alzheimer disease (1 paper, 2019). A progressive, neurodegenerative disease characterized by loss of function and death of nerve cells in several areas of the brain leading to loss of cognitive function such as memory and language. "Among the genes highlighted in the network analysis, four were also confirmed in the Alzheimer’s disease animal models: ATG3, GABARAPL2 (ATG8), MAP1LC3B, and SQSTM1." (PMID 30850634, 2019).
Aortic dissection (1 paper, 2020). Aortic dissection refers to a tear in the intimal layer of the aorta causing a separation between the intima and the medial layers of the aorta. "We speculate that the HIF1A-ATG3 axis is an important factor in the pathogenesis of TAAD, and it is necessary to address the role of ATG3 in aortic dissection." (PMID 33066131, 2020).
Azoospermia (1 paper, 2023). Absence of any measurable level of sperm,whereby spermatozoa cannot be observed even after centrifugation of the semen pellet. "Given the important role of these immune cells in azoospermia, we speculated that ATG3, KIAA0652, and MAPK1 might be implicated in azoospermia through the immune system." (PMID 36969237, 2023). "In conclusion, eight hub genes, including EGFR, HSPA5, ATG3, KIAA0652, and MAPK1 were implicated in azoospermia." (PMID 36969237, 2023).
blastoma (1 paper, 2015). A malignant neoplasm composed of undifferentiated cells. "While ATG3, ATG5, ATG7 and ATG12 are upregulated to induce autophagy in neuro-blastoma cells when G9a is inhibited." (PMID 26397365, 2015).
brain tumor (1 paper, 2023). "To assess the autophagy signal induced by IC50 doses of TMZ and EP in U87 or U87-R brain tumor cell lines, we investigated expression of autophagy pathway genes in the ULK/BECLIN1, ATG12/ATG7, and ATG3/ LC-II/autophagasome axes." (PMID 36660193, 2023).
cardiac hypertrophy (1 paper, 2024). "In the present study, we found that increased Atg3 and Atg5 levels in the heart of rats with Ang II-induced cardiac hypertrophy were suppressed after downregulation of salusins." (PMID 38336819, 2024).
chronic kidney disease (1 paper, 2017). Impairment of the renal function secondary to chronic kidney damage persisting for three or more months. "ULK1 and ATG3 are autophagy associated genes wherein the components of the process are well deciphered in chronic kidney disease by affecting the mTOR pathway." (PMID 28349958, 2017).
cyst (1 paper, 2021). A sac-like closed membranous structure that may be empty or contain fluid or amorphous material. "However, the data by microscopic examination showed that the formation of mature cyst was significantly reduced in Atg3-depleted cells." (PMID 34357992, 2021).
depression (1 paper, 2025). "Therefore, we aimed to investigate the expression and diagnostic potential of ATG3 and ATG5, as well as the relationships between these proteins and laboratory markers, depression, disease score, quality of life, and sleep in RLS patients." (PMID 39776356, 2025). "Additionally, the correlation analyses demonstrated that ATG3 was significantly correlated with the quality of sleep, while ATG5 was associated with the quality of life and depression status." (PMID 39776356, 2025). "ATG3 was substantially correlated with the quality of sleep, whereas ATG5 was correlated with the quality of life and depression status (p < 0.05)." (PMID 39776356, 2025). "The present results indicated that ATG3 was substantially correlated with the quality of sleep, whereas ATG5 was correlated with the quality of life and depression status." (PMID 39776356, 2025). "Relationship of ATG3 and ATG5 with quality of life and sleep, the depression and laboratory markers in patients with restless legs syndrome." (PMID 39776356, 2025). "Furthermore, the correlation analyses indicated that ATG3 was substantially correlated with the quality of sleep, whereas ATG5 was correlated with the quality of life and depression status." (PMID 39776356, 2025).
diabetic nephropathy (1 paper, 2026). "The VDR/Atg3 axis regulates autophagy and inhibits the development of diabetic nephropathy." (PMID 41141390, 2026).
endometriosis (1 paper, 2019). The growth of functional endometrial tissue in anatomic sites outside the uterine body. "Overexpression of EPHA3 inhibited the activation of the mTOR signaling pathway, down-regulated bcl-2 expression, up-regulated the expression of Atg3, LC3-II/LC3-I, Beclin1, bax and fas, and also promoted the autophagy and apoptosis of macrophages in endometriosis mice." (PMID 31262977, 2019).
heart failure (1 paper, 2024). Inability of the heart to pump blood at an adequate rate to meet tissue metabolic requirements. "Thus, although NAD+ deficiency plays a critical role in the development of heart failure in the mouse model of ATG3 deficiency, which blocks autophagic flux, the mechanisms underlying NAD+ deficiency are distinct from other causes of heart failure." (PMID 38212381, 2024).
herpesvirus infection (1 paper, 2024). "Additionally, myeloid-specific knockout of several autophagy genes (RB1CC1, Beclin1, ATG3, ATG5, ATG7, ATG14, or ATG16L) in animals subjected to herpesvirus infection results in elevated inflammation and prevented viral reactivation from latency." (PMID 38447109, 2024).
Hyperglycemia (1 paper, 2025). An increased concentration of glucose in the blood. "Moreover, there was an increase in the expression levels of ATG12–ATG5 complex, ATG5, and ATG3 and the conversion of LC3B-I to LC3B-II under hyperglycemia in a retinal Müller cell line." (PMID 40735446, 2025).
Hyperinsulinemia (1 paper, 2018). An increased concentration of insulin in the blood. "Next, we found that the expression of major components of the autophagy process, including Beclin-1, Atg7, Atg3, Atg12-Atg5, free Atg12, Atg16L1, and LC3II was not affected by hyperinsulinemia." (PMID 29719598, 2018).
Hypoglycemia (1 paper, 2025). A decreased concentration of glucose in the blood. "Previous studies have shown hypoglycemia in liver‐specific Atg7 knockout mice, and we now report the same in liver‐specific Atg3 knockout animals." (PMID 40420631, 2025).
inflammatory bowel disease (1 paper, 2023). A spectrum of small and large bowel inflammatory diseases of unknown etiology. "Activated Atg3- and Atg5-deficient T cells differentiated in vitro into TH9 cells show increased production of IL-9 compared to their WT counterparts, and mutations in core autophagy genes increase the risk for development of inflammatory bowel disease (IBD) in humans." (PMID 37708826, 2023).
injury (1 paper, 2024). Damage inflicted on the body as the direct or indirect result of an external force, with or without disruption of structural continuity. "In this study, we found that the HuR protein expression was inducible in the mouse model of APAP‐induced liver injury and found that HuR could protect against APAP‐induced liver injury by promoting the expression of NRF2, cyclin A1, cyclin B1, cyclin D1, CDK2, ATG3, ATG5 and ATG7." (PMID 39614424, 2024).